PRSS23 (serine protease 23)
Synonyms: ZSIG13; SPUVE; SIG13
Tractability: Antibody: UniProt places it where antibodies can reach, with high confidence; UniProt predicts a signal peptide or a membrane-spanning region; its Gene Ontology location is reachable by antibodies, with medium confidence. PROTAC: ubiquitination databases record sites on it; its protein half-life has been measured.
Gene: Protein-coding gene on chromosome 11 (86,791,059 to 86,952,910, forward strand). Ensembl gene ENSG00000150687.
Subcellular location: Secreted
Pathways (Reactome):
Metabolism of proteins: Post-translational protein phosphorylation; Regulation of Insulin-like Growth Factor (IGF) transport and uptake by Insulin-like Growth Factor Binding Proteins (IGFBPs)
Gene Ontology:
Molecular function: protein binding; serine-type endopeptidase activity
Biological process: proteolysis
Cellular component: extracellular exosome; nucleus; endoplasmic reticulum lumen; extracellular region
Genetic constraint (gnomAD): Loss-of-function variants: 25 observed, 36.57 expected, observed/expected ratio (o/e) 0.68, 90% interval 0.5 to 0.95. The upper end of that interval is the gene's LOEUF score, 0.95, which puts it in group 4 of 6, group 1 being the genes least tolerant of losing a copy. Missense variants: 445 observed, 503.09 expected, observed/expected ratio (o/e) 0.88, 90% interval 0.82 to 0.96. Synonymous variants: 176 observed, 197.48 expected, observed/expected ratio (o/e) 0.89, 90% interval 0.79 to 1.01.
Homologues: Orthologues: macaque PRSS23 (99% identical), rabbit PRSS23 (95% identical), dog PRSS23 (93% identical), guinea pig PRSS23 (93% identical), pig PRSS23 (93% identical), mouse Prss23 (91% identical), rat Prss23 (90% identical), tropical clawed frog prss23 (74% identical). Paralogues in human: PRSS35 (50% identical).
Diseases named in the same sentence as PRSS23 in open-access papers:
PRSS23 is named in the same sentence as 49 diseases in open-access papers, as found by Europe PMC text mining. Sharing a sentence is not in itself a finding about the gene and the disease. The quoted sentences say what the papers report.
breast carcinoma (7 papers, 2012 to 2025). "In cancer, PRSS23 is implicated in tumor progression, and it was identified in a systematic network survey of a meta-analysis of breast cancer microarray expression data as one of six genes involved in acquired lapatinib resistance." (PMID 34997121, 2022). "Analysis of published breast cancer microarray datasets revealed that the gene expression correlation between ERα and PRSS23 is highly significant among all ERα-associated proteases in breast cancer." (PMID 22291950, 2012). "Upregulated PRSS23 was associated with breast cancer cell proliferation, and PRSS23 knockdown could inhibit gastric cancer." (PMID 33800494, 2021). "In addition, in vitro assays revealed that PRSS23 expression was upregulated at the transcriptional level by ERα and was associated with breast cancer cell proliferation." (PMID 22291950, 2012). "Promoter studies in breast cancer cells indicated that PRSS23 is upregulated by estrogen receptor 1 (ESR1) and that its upregulated expression contributes to cell proliferation." (PMID 34997121, 2022). "Levels of PRSS23 correlate with ERα levels in breast cancer and are upregulated by ERα promoter binding." (PMID 32471474, 2020). "Our results indicate that there was a high level of PRSS23 expression in ERα-positive breast cancer cells." (PMID 22291950, 2012). "In the present study, we aimed to clarify the correlation between and functional implication of ERα and PRSS23 in breast cancer." (PMID 22291950, 2012). "Our earlier immunohistochemical data revealed that PRSS23 was located in the cell nucleus of breast cancer cells." (PMID 22291950, 2012). "Although further investigation is needed to resolve the detailed molecular mechanisms and interactions involved, we propose that PRSS23 participates in the regulation of breast cancer proliferation." (PMID 22291950, 2012). "After learning that PRSS23 expression was correlated with ERα in breast cancers, we investigated the dynamics of PRSS23 expression induced by estrogen stimulation." (PMID 22291950, 2012). "To validate the relationship between PRSS23 and ERα expression, we selected 6 representative sets of tumor samples from breast cancer patients that were either ERα-positive or ERα-negative." (PMID 22291950, 2012). "The anti-PRSS23 staining pattern in the immunohistochemical studies of the patient specimens revealed that PRSS23 is found in the cell nuclei of breast cancer cells and in normal stromal and endothelial cells of peripheral tissues." (PMID 22291950, 2012). "In conclusion, the present study highlights the potential for PRSS23 to be a novel therapeutic target in breast cancer research." (PMID 22291950, 2012). "In vitro assays in MCF-7 breast cancer cells demonstrated that PRSS23 expression is induced by 17β-estradiol-activated ERα through an interaction with an upstream promoter region of PRSS23 gene." (PMID 22291950, 2012). "Upon close examination, PRSS23 expression was found to be much higher in the nucleoplasm of ERα-positive breast cancer specimens compared with the nucleoplasm of ERα-negative breast cancer specimens." (PMID 22291950, 2012). "Histopathological assays and surveys of cancer cell lines further confirmed PRSS23 expression was significantly increased in ERα-positive breast cancers, and PRSS23 expression was upregulated by ERα-mediated transcriptional regulation." (PMID 22291950, 2012). "Strikingly, we found that nearly 75% of the ERα-positive breast cancer samples from Taiwanese patients are belonged to the group with high PRSS23 expression (Allred score>3)." (PMID 22291950, 2012). "For systemic comparison, the staining intensity of anti-PRSS23 in 56 Taiwan breast cancer samples was classified as strong, moderate, or weak." (PMID 22291950, 2012).
breast carcinoma (continued). "PRSS23 has been reported to be overexpressed in malignant pleural mesothelioma, in breast cancer cells that are positive for the ligand-binding domain of estrogen receptor-α, and in gastric cancer patients; however, in Ewing sarcoma, the expression was reduced." (PMID 40278569, 2025). "Previous studies reported that, in breast cancer cells, PRSS23 was co-expressed with estrogen receptor α (ERα), and PRSS23 knockdown may suppress estrogen-driven cell proliferation of breast cancer cells." (PMID 34111027, 2021). "Clinicopathological characteristics and PRSS23 expression profile of breast cancer specimens." (PMID 22291950, 2012). "Our findings imply that PRSS23 might be a critical component of estrogen-mediated cell proliferation of ERα-positive breast cancer cells." (PMID 22291950, 2012). "We also investigated the functional role of PRSS23 and found that PRSS23 may regulate DNA replication during cancer cell proliferation, which highlights PRSS23's potential as a novel target for breast cancer therapy." (PMID 22291950, 2012). "We then assessed PRSS23 expression in 56 primary breast cancer biopsies and 8 cancer cell lines." (PMID 22291950, 2012). "Based on these findings, we hypothesized that PRSS23 might be involved in estrogen-driven mechanisms to mediate chromosome replication of ERα-positive breast cancer cells." (PMID 22291950, 2012). "Interestingly, PRSS23 is coexpressed with estrogen receptor α (ERα), which is a prominent biomarker and therapeutic target for human breast cancer." (PMID 22291950, 2012). "In addition to being significantly coregulated with ESR1 expression, the present results suggest that there is greater mRNA expression level of PRSS23 in breast cancer specimen than other well-known cancer-related proteases." (PMID 22291950, 2012). "In conclusion, the present study demonstrated the close relationship between PRSS23 and estrogen/ERα signaling in breast cancer, which might serve as the basis for developing PRSS23 into a novel prognostic or therapeutic target for breast cancer." (PMID 22291950, 2012). "Therefore, it is plausible to hypothesize that protein levels of PRSS23 might also serve as an independent prognostic factor for breast cancer." (PMID 22291950, 2012). "Thus, we used an RNAi knockdown approach to examine cancer cell function could be affected by PRSS23 on breast cancer cell proliferation." (PMID 22291950, 2012). "Thus, PRSS23 might be a novel target for adjuvant therapy for breast cancer progression." (PMID 22291950, 2012). "We also compared the expression intensities of PRSS23, CTSC, CTSF, and MMP-24 from 52 ERα-positive breast cancer specimens within the van't Veer dataset." (PMID 22291950, 2012). "Because the expression of PRSS23 in breast cancer has not been clearly characterized, we targeted PRSS23 for further analysis in the present study." (PMID 22291950, 2012).
gastric cancer (5 papers, 2020 to 2025). A primary or metastatic malignant neoplasm involving the stomach. "Further in vitro experiments revealed that PRSS23 knockdown in gastric cancer cells apparently affected EIF2 pathway molecules." (PMID 34997121, 2022). "In this study, the prognostic significance of PRSS23 was analyzed in two-independent gastric cancer (GC) cohorts." (PMID 36189305, 2022). "Moreover, knockdown of PRSS23 could inhibit EIF2 signaling, thereby suppressing the tumor growth of gastric cancer." (PMID 32582282, 2020).
renal fibrosis (3 papers, 2021 to 2023). A final common manifestation of a wide variety of chronic kidney diseases characterized by glomerulosclerosis and tubulointerstitial fibrosis. "IgAN podocytes had increased expression of the serine protease PRSS23, which has been demonstrated to be highly expressed in the glomeruli of human fibrotic kidneys and may play a pathogenic role in renal fibrosis." (PMID 33936064, 2021). "Prss23, by contrast, has an established role as an antifibrotic agent in the context of renal fibrosis but is again understudied in the context of respiratory viral infection." (PMID 37852965, 2023). "Elevated HE4 inhibits the degradation of collagen I by inhibiting the activity of serine proteases (Prss23 and Prss35) and matrix metalloproteinases (MMP-2 and MMP-9) and accelerates the deposition of type I collagen in the kidneys, leading to renal fibrosis." (PMID 37753112, 2023).
dementia (2 papers, 2023). Loss of intellectual abilities interfering with an individual's social and occupational functions. "Four genes (FGFBP2, PRSS23, TGFBR3, NUAK1) out of the 5 top IL-7Rαlow aging genes remained differentially expressed with decreased relative gene expression in the dementia group compared to the MCI group." (PMID 38042785, 2023). "Four genes (FGFBP2, PRSS23, TGFBR3, NUAK1) out of 5 top IL-7Rαlow aging genes remained differentially expressed at the P < 0.05 significance level after Šidák correction with decreased relative gene expression in the dementia group compared to the MCI group." (PMID 37066364, 2023).
focal segment glomerulosclerosis (2 papers, 2020 to 2023). "Further support for a role for PRSS23 in kidney function comes from transcriptome studies of patients with focal segment glomerulosclerosis (FSGS), which is a major cause of end stage renal disease." (PMID 37580336, 2023).
glomerular disease (2 papers, 2023 to 2024). "Bulk RNA-seq results also confirmed the reduced expression of PRSS23 in various glomerular diseases." (PMID 37908345, 2023).
lung carcinoma (2 papers, 2021 to 2023). "Our observation of the associations between cg14391737, an intronic POE-CpG located of the gene PRSS23, with smoking status and forced expiratory flow, was in line with the previous MWAS papers that identified cg14391737 as a smoking- and lung cancer-associated CpG." (PMID 37189164, 2023).
pancreatic cancer (2 papers, 2012 to 2022). "In head and neck, renal, and pancreatic cancer, PRSS23 expression is significantly associated with an unfavorable prognosis." (PMID 34997121, 2022). "Previous expression-profiling studies have suggested that enhanced PRSS23 expression is observed in various types of cancers, including breast, prostate, papillary thyroid, and pancreatic cancers, and the expression of the PRSS23 has been linked with tumor progression in human." (PMID 22291950, 2012).
pancreatic ductal adenocarcinoma (2 papers, 2020 to 2021). An infiltrating adenocarcinoma that arises from the epithelial cells of the pancreas. "Interestingly, in a recent study sharing analogies with our work, PRSS23 was found to be a component of an 18-gene molecular signature associated with the OS of patients affected by pancreatic ductal adenocarcinoma." (PMID 33800494, 2021).
scleroderma (2 papers, 2023 to 2025). Scleroderma is a rare autoimmune connective tissue disorder characterized by abnormal hardening of the skin and, sometimes, other organs. "Our fibroblasts in NEOLP and EOLP shared transcriptional similarity with fibroblasts from skins of scleroderma patients (including CCL19+APOE+CXCL12+ fibroblasts and SFRP2+PRSS23+ fibroblasts), which indicated an overlap between inflammatory features of fibroblasts across OLP and other diseases." (PMID 40574847, 2025). "Additionally, a variety of other genes associated with inflammatory as well as malignant diseases were enriched in scleroderma fibroblasts (POSTN, PRSS23, TNC, and SERPINE2)." (PMID 37443817, 2023).
breast tumors (1 paper, 2012). "We used the custom anti-PRSS23 antibody to perform immunohistochemical assays on cancer specimens from 56 primary breast tumors collected in Taiwan." (PMID 22291950, 2012). "Interestingly, PRSS23 expression was detected in the nuclei of malignant breast tumor tissues." (PMID 22291950, 2012).
clear cell ovarian carcinoma (1 paper, 2026). "In contrast, PRSS23 knockdown reduced proliferation and increased anoikis sensitivity in high-grade serous and clear cell ovarian carcinoma cell lines and diminished tumor establishment, dissemination, and ascites in intraperitoneal xenograft models." (PMID 41985786, 2026).
colon carcinoma (1 paper, 2022). "Among differentially expressed genes (DEGs), serine protease 23 (PRSS23) was upregulated in four datasets, i.e., in human colon carcinoma cells, mouse heart tissue, mouse neural stem cells, and human glioma cells." (PMID 34997121, 2022). "Serine protease 23 (PRSS23) was upregulated in four datasets, i.e., human colon carcinoma cells, mouse heart tissue, mouse neural stem cells, and human glioma cells." (PMID 34997121, 2022).
infarcts (1 paper, 2025). "Notably, LTBP1 and CRIP1, along with C1QC and PRSS23 (linked to WMH and infarcts) and CEMIP and ELN (associated with WMH and microbleeds), showed strong co-localization with ThioS- positive vascular amyloid deposits, but not with parenchymal plaques." (PMID 41282800, 2025).
nicotine addiction (1 paper, 2021). "This study aimed to evaluate the DNA methylation levels of cg05575921 (AHRR) and cg23771366 (PRSS23) and their correlation with lung function variables, cigarette consumption, and nicotine addiction in the Mexican smoking population." (PMID 34440450, 2021). "This study aimed to evaluate the DNA methylation level of cg05575921 (AHRR) and cg23771366 (PRSS23) and their correlation with lung function variables, cigarette consumption, and nicotine addiction in the Mexican smoking population." (PMID 34440450, 2021).
ovarian carcinoma (1 paper, 2026). A malignant neoplasm originating from the surface ovarian epithelium. "Together, these findings demonstrate protease-independent PRSS23 function in ovarian cancer peritoneal dissemination and suggest that PRSS23 may ultimately warrant reclassification as a serine pseudoprotease." (PMID 41985786, 2026).
sarcoidosis (1 paper, 2025). Sarcoidosis is a multisystemic disorder of unknown cause characterized by the formation of immune granulomas in involved organs. "Reanalysis of a sarcoidosis scRNA-seq dataset revealed that, similar to NL and NXG, sarcoidosis lesional fibroblasts expressed high levels of MHC (e.g., HLA-B and HLA-DRA), CD74, PLOD2, STAT1, TNC, PRSS23, PSMB9, and CXCL9." (PMID 39989459, 2025).
viral infection (1 paper, 2020). "The club cells also expressed high levels of protease-related genes (PRSS23, CTSC), that together with anti-proteases, are important for the susceptibility to viral infection." (PMID 32727470, 2020).
tumor (15 papers, 2012 to 2026). "Mechanismly, PRSS23 promotes tumor associated macrophage infiltration by regulating FGF2 expression and secretion." (PMID 36189305, 2022). "PRSS23 functions as an oncogene in GC by enhancing tumor associated macrophage infiltration via FGF2." (PMID 36189305, 2022). "Serine protease PRSS23 is known to be associated with tumor progression in various types of cancers and is co-expressed with estrogen receptor α (ERα)." (PMID 31303963, 2019). "Serine protease PRSS23 is a newly discovered protein that has been associated with tumor progression in various types of cancers." (PMID 22291950, 2012). "Unsurprisingly, these genes have been previously associated with tumor growth and metastasis (NUAK1, TGFBR3, FGFBP2), as well as autoimmune disorders (PRSS23)." (PMID 37066364, 2023). "These genes have been previously associated with tumor growth and metastasis (NUAK1, TGFBR3, FGFBP2), as well as autoimmune disorders (PRSS23)." (PMID 38042785, 2023). "The results showed that both PRSS23 and FGF2 were significantly overexpressed in M2 macrophage, which is highly similar to tumor associated macrophage." (PMID 36189305, 2022). "Single-cell analysis and gene expression correlation analysis showed that PRSS23 and FGF2 were high expressed in fibroblasts, and highly co-expressed with the biomarkers of tumor associated macrophages (TAMs), cancer-associated fibroblasts (CAFs) and mesenchymal cells." (PMID 36189305, 2022). "These sites were annotated to genes involved in diverse biological pathways, including neurological development (AHNAK, PGAP3), lymphocytic function (ITGAL), apoptosis (RELT), tumor suppression (ZGPAT), and endothelial-to-mesenchymal transition (PRSS23)." (PMID 32084330, 2020).